PPP2R2B (protein phosphatase 2 regulatory subunit Bbeta)
Description:
The B regulatory subunit might modulate substrate selectivity and catalytic activity, and might also direct the localization of the catalytic enzyme to a particular subcellular compartment. Within the PP2A holoenzyme complex, isoform 2 is required to promote proapoptotic activity (By similarity). Isoform 2 regulates neuronal survival through the mitochondrial fission and fusion balance (By similarity).
Synonyms: PR55-BETA; PR52B; B55beta; PP2AB55BETA; PP2ABBETA; PP2APR55B; PP2APR55BETA; PR2AB55BETA; PR2ABBETA; PR2APR55BETA; PR55BETA; SCA12
Tractability: PROTAC: ubiquitination databases record sites on it; its protein half-life has been measured.
Gene: Protein-coding gene on chromosome 5 (146,580,742 to 147,084,784, reverse strand). Ensembl gene ENSG00000156475.
Subcellular location: Cytoplasm (Isoform 1); Cytoplasm, cytoskeleton; Membrane; Cytoplasm (Isoform 2); Mitochondrion; Mitochondrion outer membrane
Subcellular location (Human Protein Atlas): Cytosol
Gene Ontology:
Molecular function: protein binding; protein phosphatase regulator activity
Cellular component: protein phosphatase type 2A complex; cytosol; mitochondrial outer membrane; mitochondrion; cytoplasm; cytoskeleton; membrane
Genetic constraint (gnomAD): Loss-of-function variants: 3 observed, 44.71 expected, observed/expected ratio (o/e) 0.0671, 90% interval 0.03 to 0.17. The upper end of that interval is the gene's LOEUF score, 0.17, which puts it in group 1 of 6, group 1 being the genes least tolerant of losing a copy. Missense variants: 365 observed, 601.71 expected, observed/expected ratio (o/e) 0.61, 90% interval 0.56 to 0.66. Synonymous variants: 215 observed, 219.11 expected, observed/expected ratio (o/e) 0.98, 90% interval 0.88 to 1.1.
Homologues: Orthologues: chimpanzee PPP2R2B (100% identical), macaque PPP2R2B (100% identical), mouse Ppp2r2b (100% identical), rabbit PPP2R2B (100% identical), pig PPP2R2B (99% identical), dog PPP2R2B (99% identical), rat Ppp2r2b (99% identical), guinea pig PPP2R2B (96% identical), tropical clawed frog ppp2r2b (92% identical), Caenorhabditis elegans sur-6 (65% identical). Paralogues in human: PPP2R2C (87% identical), PPP2R2A (85% identical), PPP2R2D (85% identical).
Diseases named in the same sentence as PPP2R2B in open-access papers:
PPP2R2B is named in the same sentence as 95 diseases in open-access papers, as found by Europe PMC text mining. Sharing a sentence is not in itself a finding about the gene and the disease. The quoted sentences say what the papers report.
breast carcinoma (17 papers, 2010 to 2025). "Collectively, these clinical data established a strong association of PPP2R2B expression with clinical outcome of HER2+ breast cancer and suggested a potential role for PPP2R2B in determining the sensitivity of anti-HER2 therapies." (PMID 33208750, 2020). "The variants of the PPP2R2B gene were primarily located in introns, similar to another study that also identified one genetic variant in the intron of the PPP2R2B gene and found it to be associated with altered breast cancer risk and recurrence." (PMID 32131721, 2020). "In breast cancer patients, a variant of the rs319217 SNP in PPP2R2B is associated with a better response to chemotherapy treatment and lower risk of breast cancer recurrence." (PMID 27888627, 2016). "More recently, a study indicated that the A variant of a SNP (rs319217 A>G) in the PPP2R2B gene is a marker for improved prognosis of breast cancer." (PMID 22539979, 2012). "In breast cancer, PPP2R2B expression was strongly associated with immune check point inhibitor genes such as BZMA, PRF1, and IFNG, suggesting that downregulation of PPP2R2B could take part in tumor immune evasion." (PMID 39851522, 2025). "Q-PCR assays showed that PPP2R2B could associate with the early-onset of breast cancer, and the malignant progression of TNBC." (PMID 33407498, 2021). "We demonstrated that PP2A regulatory subunit PPP2R2B is a major subunit of PP2A whose downregulation is associated with poor prognosis in HER2+ breast cancer and resistance to anti-HER2 treatments, including both HER2-targeting antibody trastuzumab and HER2 kinase inhibitor lapatinib." (PMID 33208750, 2020). "PPP2R2B, encoding B55β, is frequently inactivated by methylation in breast tumors and a genetic variant in this gene associates with altered breast cancer risk and recurrence, thus suggesting that PP2A-B55 complexes may play a tumor suppressor role in breast cancer." (PMID 29229993, 2018). "In breast cancer, the expression level of PPP2R2B is significantly correlated with a longer distant metastasis-free survival and recurrence-free survival." (PMID 36512456, 2023). "Quantitative real-time PCR assay (Q-PCR) was carried out to assess the role of PPP2R2B in the onset and progression of breast cancer." (PMID 33407498, 2021). "Our findings support future clinical studies to investigate the clinical utility of this combination strategy for treating HER2+ breast cancer while evaluating PPP2R2B as a potential predictive marker of anti-HER2 therapy." (PMID 33208750, 2020). "PPP2R2B is downregulated in a substantial subset of HER2+ breast cancers, which correlates with poor clinical outcome and resistance to HER2-targeted therapies." (PMID 33208750, 2020). "Here, the authors demonstrate that EZH2 regulates response to HER2-targeting therapies in breast cancer, in part, by modulating the expression of PPP2R2B." (PMID 33208750, 2020). "We confirmed that PPP2R2B-associated PP2A targets p70S6K and 4EBP1 for dephosphorylation, and thus reduced expression of PPP2R2B in breast cancer cells is associated with diminished p70S6K and 4EBP1 dephosphorylation by anti-HER2 treatment." (PMID 33208750, 2020). "In both public database and our in-house patient specimens, PPP2R2B downregulation occurred in about 50% of HER2+ breast cancers compared to normal tissues." (PMID 33208750, 2020). "Breast cancer specific survival was significantly improved in patients with hyper-methylated promoters for PPP2R2B (p = 0.012)." (PMID 24093668, 2013). "We report here for the first time the PPP2R2B methylation status as significant predictor for breast cancer survival as well as for overall survival." (PMID 24093668, 2013). "It has been reported that hypomethylation of the PP2A-B55β gene (PPP2R2B) promoter induces its expression, which was found to be involved in the expression of estrogen receptors (ERs) in human breast cancer cell lines." (PMID 23555712, 2013).
breast carcinoma (continued). "Univariate survival analysis identifies methylation status of PPP2R2B as significant predictor of overall survival and breast cancer specific survival." (PMID 24093668, 2013). "Moreover, EZH2 inhibitors can activate PPP2R2B expression, thus increasing breast cancer sensitivity to anti-HER2 therapy." (PMID 38976080, 2024). "Based on the Q-PCR assay, we speculated that PPP2R2B may participate in the development and progression of breast cancer." (PMID 33407498, 2021). "Q-PCR analysis suggested that PPP2R2B downregulation could play a key role in breast-cancer initiation and progression." (PMID 33407498, 2021). "In addition to DMFS, PPP2R2B downregulation, among the seven candiates, is also associated with poor RFS, as well as poor overall survival (OS) in HER2+ breast cancer patients." (PMID 33208750, 2020). "Recent studies have reported that PPP2R2B is a robust tumor suppressor and plays an important role in anti-tumor immune responses, and that its dysregulation could contribute to the onset and progression of breast cancer." (PMID 36612032, 2022). "Thus, dysregulation of PPP2R2B expression could serve as a pathologic driver of breast cancer, implicating its potential value as a candidate predictive biomarker and therapeutic target." (PMID 33407498, 2021). "In this study, we identified PPP2R2B as a robust tumor suppressor, and played an important role in anti-tumor immune response, which dysregulation could contribute to the onset and progression of breast cancer." (PMID 33407498, 2021). "Another studied gene,PPP2R2B on 5q31-q32 encodes the regulatory subunit of the protein phosphates 2A complex (PP2A) and has been proposed as a tumour suppressor gene candidate due to its negative control of cell growth and the high frequency of LOH in breast cancers." (PMID 20338046, 2010). "PPP2R2B silencing is reported to be due to promoter DNA methylation in colorectal cancer and trimethylation of H3K27 in breast cancer." (PMID 38976080, 2024). "The observation that PPP2R2B, among all the PP2A subunits, is most prognostic in HER2+ breast cancer, supports its role in impacting the treatment outcome of trastuzumab." (PMID 33208750, 2020). "In addition to mutations in the scaffold subunits, B55α (encoded by the PPP2R2A gene) and B55β (encoded by PPP2R2B) subunits are occasionally eliminated by deletion or hypermethylation of the corresponding genes suggesting the relevance of PP2A-B55 activity in preventing breast cancer development." (PMID 29229993, 2018). "In the present study, five genes, ABCB1, FOXC1, GSTP1, PPP2R2B and RASSF1A were hypermethylated already in early stage breast cancer (stage I and II)." (PMID 24093668, 2013). "Genetic depletion or inhibition of EZH2 by a clinically-available EZH2 inhibitor restores PPP2R2B expression, abolishes the residual phosphorylation of p70S6K and 4EBP1, and resensitizes HER2+ breast cancer cells to anti-HER2 treatments both in vitro and in vivo." (PMID 33208750, 2020). "Collectively, these findings suggest that EZH2 directly represses PPP2R2B expression through chromatin modification, and small molecule inhibition of EZH2 restored PPP2R2B expression and abolished the residual p70S6K and 4EBP1 activity in breast cancer." (PMID 33208750, 2020). "Currently, most HER2+ breast cancer patients are treated with anti-HER2 therapies, and because a substantial fraction of treated patients later suffers distant relapse relapses due to therapy resistance, we sought to determine the relationship between PPP2R2B expression and therapeutic outcome." (PMID 33208750, 2020).
breast carcinoma (continued). "Further, we identified four novel genes (ABCB1, FOXC1, PPP2R2B and PTEN) that were found to be already aberrantly methylated in DCIS (Ductal carcinoma in situ), a pre-invasive stage of breast cancer and that were also found to be methylated in the locally advanced breast cancers." (PMID 24093668, 2013). "Interestingly, PPP2R2B was found to be the most significant (P < 0.01) in its association with distant metastasis-free survival (DMFS) in HER2+ breast cancer, but not in basal-like, luminal A, or luminal B breast cancer subtypes." (PMID 33208750, 2020). "Here we report aberrant methylation levels of ABCB1, FOXC1, GSTP1, PPP2R2B and RASSF1A in DCIS and stage I-IV providing evidence that suggests that changes in methylation level is an early event and may also be important in progression to later stages of breast cancer." (PMID 24093668, 2013).
spinocerebellar ataxia (17 papers, 2012 to 2025). "In contrast, mutations in PPP2R3C (encoding the regulatory B′′γ or G5PR subunit) were found to be mainly associated with deficits in gonadal development, and mutations in the promotor of PPP2R2B (encoding B55β) with spinocerebellar ataxia." (PMID 36313552, 2022). "Protein phosphatase 2 regulatory subunit B beta (PPP2R2B) is a protein-coding gene associated with diseases including spinocerebellar ataxia, and in our study, it is associated with favorable survival." (PMID 33816503, 2021). "PPP2R2B encodes a brain specific regulatory subunit of a protein phosphatase and is the causal locus for a Mendelian disease, a form of spinocerebellar ataxia (SCA12, OMIM# 604326)." (PMID 22369142, 2012). "This study involved six genes (ATXN1, ATXN3, ATXN7, HTT, NOP56, and PPP2R2B), while a higher detection rate has been reported in a spinocerebellar ataxia cohort (4.4%, 22/498), which included five genes (ATXN2, ATXN3, NOP56, AR and HTT)." (PMID 38308084, 2024). "Abnormal expression of the PPP2R2B gene leads to spinocerebellar ataxia, which leads to a gradual weakening of eye movement coordination in patients." (PMID 36553670, 2022). "His MRI brain showed cerebellar atrophy and a genetic screen for spinocerebellar ataxia subtypes showed a CAG repeat length of 54 repeats in PPP2R2B gene." (PMID 35531119, 2022). "However, his MRI brain of the patient showed cerebral and cerebellar atrophy and a genetic screen for spinocerebellar ataxia subtypes showed a CAG repeat length of 42 repeats in PPP2R2B gene." (PMID 35531119, 2022). "RT-qPCR revealed that the mRNA transcription levels of four ataxia-related genes (ataxin 10 (Atxn10), protein phosphatase 2 regulatory subunit B beta (Ppp2r2b), protein kinase C gamma (Prkcg), and phospholipase D3 (Pld3)) were significantly changed in the Zfp212-KO Cb compared to those in the WT." (PMID 34815492, 2021). "The frequency is followed by ATXN7: 6.09%, TBP: 5.59%, ATXN2: 5.03%, CACNA1A: 4.28%, PPP2R2B: 2.68%, and ATXN3: 2.42% with respective cutoff values in uncharacterized ataxia cases." (PMID 36618024, 2022).
spinocerebellar ataxia type 12 (9 papers, 2017 to 2025). Spinocerebellar ataxia type 12 (SCA12) is a very rare subtype of type I autosomal dominant cerebellar ataxia (ADCA type I). "A CAG repeat expansion in the neuron-specific protein PP2A regulatory subunit PPP2R2B gene causes spinocerebellar ataxia type 12 (SCA12)." (PMID 39565297, 2025). "Spinocerebellar ataxia type 12 (SCA12) is a rare autosomal dominant neurodegenerative disorder caused by abnormal CAG repeat expansion in the PPP2R2B gene." (PMID 39469072, 2024). "Triplet expansion in PPP2R2B causes spinocerebellar ataxia type 12, but variation in this gene had not previously been associated with Alzheimer’s disease in humans." (PMID 33426524, 2020). "CAG repeat expansions in the gene PPP2R2B, which encodes for protein phosphatase 2, has been genetically linked to spinocerebellar ataxia type 12 (SCA12)." (PMID 29186753, 2017). "We tested this idea by attempting to generate isogenic iPSC lines with different lengths of the CAG repeat in exon 7 of human PPP2R2B gene, part of our long term goal of generating cell models of spinocerebellar ataxia type 12 (SCA12), a disorder caused by expanded CAG repeats at this locus." (PMID 33972655, 2021). "We also included PPP2R2B and DMPK, expansions of CAG•CTG repeats within which underlie spinocerebellar ataxia type 12 (SCA12, MIM #604326) and myotonic dystrophy type 1 (DM1, MIM #160900), respectively, but are not translated into polyglutamine." (PMID 38449714, 2024). "Indeed, the discovery that spinocerebellar ataxia 12 is caused by a similar transcribed CAG repeat expansion at PPP2R2B that does not produce polyglutamine, argues that other mechanisms must also be considered as potential toxicity drivers in the various CAG repeat diseases." (PMID 31398342, 2019). "A PPP2R2B variation confirmed spinocerebellar ataxia type 12 (SCA12), a condition not previously considered because classical cerebellar signs were absent." (PMID 38854909, 2024).
dentatorubral-pallidoluysian atrophy (8 papers, 2012 to 2025). Dentatorubral pallidoluysian atrophy (DRPLA) is a rare subtype of type I autosomal dominant cerebellar ataxia (ADCA type I). "Genes that were part of this signature on the brain side were the TCF4, ATN1, PPP2R2B, ATXN10 and ATXN3, which are associated with neurodegenerative and developmental disorders such as Pitt-Hopkins Syndrome, Dentatorubral pallidoluysian atrophy, SCA12, SCA10 and SCA3." (PMID 27476530, 2016).
dementia (5 papers, 2013 to 2022). Loss of intellectual abilities interfering with an individual's social and occupational functions. "As for mutation in the non-coding area, patients with SCA8, SCA10, and SCA12 present cognitive dysfunction or dementia, (CTG)n repeats in Ataxin8 3'UTR causes SCA8, (ATTCT)n in Ataxin10 intron results in SCA10, and (CAG)n in PPP2R2B 5'UTR leads to SCA12." (PMID 35478698, 2022). "Among the six PP2A proteins, three proteins (PPP2R2B, PPP2CA, and PPP2R1A) are also listed in the highly ranked proteins in the dementia network, demonstrating their centrality." (PMID 24908109, 2014).
colorectal cancer (4 papers, 2016 to 2024). A primary or metastatic malignant neoplasm that affects the colon or rectum. "It has been reported that, in colorectal cancer, PPP2R2B, encoding the B55β regulatory subunit of the PP2A complex, is epigenetically inactivated by DNA hypermethylation and is related to the rapamycin sensitization." (PMID 33816503, 2021). "As far as PPP2R2B is concerned, recent studies show that its promoter is methylated in colorectal cancer, ductal carcinoma in situ, and early invasive breast cancer, as well as laryngeal squamous cell carcinoma." (PMID 26337424, 2016).
lung carcinoma (4 papers, 2013 to 2021). "The roles of PPP2R2B in lung cancer need further exploration." (PMID 33816503, 2021).
nasopharyngeal carcinoma (4 papers, 2015 to 2020). A carcinoma arising from the nasopharyngeal epithelium. "In nasopharyngeal carcinoma, reduced PPP2R2B expression activates PDK1/MYC pathways to induce BEZ235 resistance." (PMID 27888627, 2016). "We speculate that a PPP2R2B deficiency can induce MYC and P70 phosphorylation by impairing the binding of PP2A and MYC as well as PP2A and P70, thus modulating nasopharyngeal carcinoma resistance to BEZ235." (PMID 25762617, 2015). "Reduced PTEN and PPP2R2B expression correlated with activated AKT/mTOR and PDK1/MYC pathways and conferred considerable BEZ235 resistance in nasopharyngeal carcinoma." (PMID 25762617, 2015). "Reduced PTEN and PPP2R2B expression correlated with activated AKT/mTOR and PDK1/MYC pathways, which can confer considerable BEZ235 resistance in nasopharyngeal carcinoma." (PMID 25762617, 2015).
Intellectual disability (3 papers, 2022 to 2025). "We established five monoallelic missense variants in PPP2R2B (four confirmed as de novo) as a cause of intellectual disability with developmental delay (R149P, T246K, N310K, E37K, I427T)." (PMID 39565297, 2025). "In conclusion, our studies identify loss-of-function at the PPP2R2B locus as the basis for syndromic intellectual disability with developmental delay." (PMID 39565297, 2025). "Some studies suggested that DNMs in the PPP2R2B gene may partially contribute to the genetic landscape of intellectual disability, but we found only one study linking this gene to ASD." (PMID 36199823, 2022).
Alzheimer disease (2 papers, 2012 to 2020). A progressive, neurodegenerative disease characterized by loss of function and death of nerve cells in several areas of the brain leading to loss of cognitive function such as memory and language. "For comparison, voxel-wise analyses for APOE ɛ4 showed only modest focal medial temporal signal, in contrast to the robust Alzheimer’s disease pattern of association seen for the PPP2R2B and IGF2BP3 SNPs identified through GWAS." (PMID 33426524, 2020). "In addition, a study suggested that a CAG repeat polymorphism in the PPP2R2B gene may be functional and may, in part, play a role in conferring susceptibility to Alzheimer's disease (AD) and essential tremor (ET) in Taiwan." (PMID 22539979, 2012). "Based on an atlas of single cell gene expression from entorhinal cortex tissue samples, PPP2R2B has lower expression in Alzheimer’s disease compared to controls in numerous cell types, with the strongest association in oligodendrocytes (FDR-corrected P = 8.92 × 10−171)." (PMID 33426524, 2020).